CEP78 (centrosomal protein 78)
Description:
Centriole wall protein that localizes to mature centrioles and regulates centriole and cilia biogenesis. Involved in centrosome duplication: required for efficient PLK4 centrosomal localization and PLK4-induced overduplication of centrioles. Involved in cilium biogenesis and controls cilium length. Acts as a regulator of protein stability by preventing ubiquitination of centrosomal proteins, such as CCP110 and tektins. Associates with the EDVP complex, preventing ubiquitination and degradation of CCP110. Promotes deubiquitination of tektin proteins (TEKT1, TEKT2, TEK3, TEKT4 and TEKT5) via its interaction with USP16 (By similarity).
Synonyms: C9orf81; FLJ12643; CRDHL; IP63
Tractability: PROTAC: ubiquitination databases record sites on it.
Gene: Protein-coding gene on chromosome 9 (78,236,042 to 78,279,690, forward strand). Ensembl gene ENSG00000148019.
Subcellular location: Cytoplasm, cytoskeleton, microtubule organizing center, centrosome; Cytoplasm, cytoskeleton, microtubule organizing center, centrosome, centriole; Cytoplasm, cytoskeleton, cilium basal body
Pathways (Reactome):
Cell Cycle: AURKA Activation by TPX2; Loss of Nlp from mitotic centrosomes; Loss of proteins required for interphase microtubule organization from the centrosome; Recruitment of NuMA to mitotic centrosomes; Recruitment of mitotic centrosome proteins and complexes; Regulation of PLK1 Activity at G2/M Transition
Organelle biogenesis and maintenance: Anchoring of the basal body to the plasma membrane
Gene Ontology:
Biological process: cilium organization; flagellated sperm motility; negative regulation of protein ubiquitination; protein localization to centrosome; protein localization to cilium
Cellular component: centriole; centrosome; ciliary basal body; cytosol
Genetic constraint (gnomAD): Loss-of-function variants: 44 observed, 36.94 expected, observed/expected ratio (o/e) 1.19, 90% interval 0.94 to 1.53. The upper end of that interval is the gene's LOEUF score, 1.53, which puts it in group 6 of 6, group 1 being the genes least tolerant of losing a copy. Missense variants: 592 observed, 527.26 expected, observed/expected ratio (o/e) 1.12, 90% interval 1.05 to 1.2. Synonymous variants: 201 observed, 196.54 expected, observed/expected ratio (o/e) 1.02, 90% interval 0.91 to 1.15.
Gene-disease validity (ClinGen):
ClinGen rates the evidence that CEP78 causes each of these diseases.
cone-rod dystrophy and hearing loss (autosomal recessive): Strong. Inherited ocular disorder, characterised by the loss of cone cells, and hearing loss.
Homologues: Orthologues: chimpanzee CEP78 (99% identical), macaque CEP78 (97% identical), rabbit CEP78 (88% identical), dog CEP78 (88% identical), pig CEP78 (86% identical), mouse Cep78 (78% identical), rat Cep78 (77% identical), guinea pig CEP78 (71% identical), tropical clawed frog cep78 (51% identical), zebrafish cep78 (41% identical), Drosophila melanogaster CG7886 (22% identical).
Diseases named in the same sentence as CEP78 in open-access papers:
CEP78 is named in the same sentence as 27 diseases in open-access papers, as found by Europe PMC text mining. Sharing a sentence is not in itself a finding about the gene and the disease. The quoted sentences say what the papers report.
cone-rod dystrophy (10 papers, 2018 to 2025). Inherited retinal dystrophies that belong to the group of pigmentary retinopathies. "For instance, CEP78 encodes a centrosomal protein involved in cilia formation and in the regulation of ciliary length, and is responsible for a cone-rod dystrophy with early onset SNHL." (PMID 39672920, 2025). "CEP78: Homozygous and compound heterozygous CEP78 variants have been found to cause cone-rod dystrophy in some families." (PMID 40149483, 2025). "CEP78 is a centrosomal protein implicated in ciliogenesis and ciliary length control, and mutations in the CEP78 gene cause retinal cone-rod dystrophy associated with hearing loss." (PMID 34259627, 2021). "Participant 3 (P3), a 66-year-old male, presented with a cone-rod dystrophy and hearing loss due to a homozygous deletion-inversion-deletion overlapping CEP78 (MIM: 617110)." (PMID 30526634, 2018). "We present a case (subject 20) with early-onset pericentral rod-cone dystrophy who had clinical sequencing that identified 2 pathogenic variants, 1 coding a single nucleotide variant (SNV) and 1 SV, in the CEP78 gene." (PMID 39264853, 2024). "Two patients, 39 and 40, suffered from another ciliopathy, namely cone-rod dystrophy and hearing loss 1 (CRDHL1; OMIM 617236), due to homozygous or compound heterozygous variants in CEP78, respectively." (PMID 34148116, 2022). "Patient F8-III:5 in our study had a homozygous missense mutation c.830T > C (p.L277P) in CEP78 and presented cone and rod dystrophy without hearing impairment." (PMID 34130719, 2021).
hearing loss (8 papers, 2018 to 2024). "As for CEP250, several biallelic pathogenic variants of CEP78 have been reported in patients presenting with progressive and late-onset cone–rod degeneration and hearing loss." (PMID 35353227, 2022). "The mutation is very likely to be the genetic cause based on the evidences above, but the phenotype is unusual as all patients reported to harbor CEP78 mutations have hearing impairment." (PMID 34130719, 2021). "For instance, the combination of WES, qPCR, and TGS was able to unravel for the first-time novel SVs of centrosomal protein 78 (CEP78), a key gene responsible for hearing loss associated with cone–rod dystrophy (CRDHL)." (PMID 37892216, 2023).
Usher syndrome (5 papers, 2017 to 2023). A syndromic diseae characterized by the association of sensorineural deafness (usually congenital) with retinitis pigmentosa and progressive vision loss. "CEP78 has been reported to be related to the pathogenesis of Usher syndrome or cone dystrophy along with sensory hearing loss in recent studies." (PMID 34130719, 2021). "Inactivating variants as well as a missense variant in the centrosomal CEP78 gene have been identified in autosomal recessive cone-rod dystrophy with hearing loss (CRDHL), a rare syndromic inherited retinal disease distinct from Usher syndrome." (PMID 33968938, 2021). "PDZD7 may act as a modifier gene for USH, but HARS, ABHD12, CIB2, CEP250, CEP78, ESPN, and ARSG could be grouped in a separate syndromic “deaf–blindness” category, to avoid diagnostic pitfalls and misinformation during genetic counseling for Usher syndrome." (PMID 35353227, 2022). "To conclude, this study supports that the CEP78 locus is prone to microhomology-mediated, replication-based SV formation and that (complex) SV analysis should be included in molecular genetic testing of CRDHL or “atypical” Usher syndrome." (PMID 33968938, 2021).
male infertility (3 papers, 2023 to 2025). The inability of the male to effect fertilization of an ovum after a specified period of unprotected intercourse. "Aberrant spermiogenesis resulting in a similar phenotype has been previously observed when the centrosomal gene Cep78 is mutated, which resulted in low sperm count, impaired sperm motility, abnormal sperm morphology, and ultimately male infertility." (PMID 40294089, 2025). "It is associated with male infertility in humans, where a pathogenic splice mutation in CEP78 was identified in patients with severely reduced sperm counts and motility, as well as multiple sperm morphological abnormalities." (PMID 38540441, 2024). "The major findings of our study are as follows: we found CEP78 as the causal gene of CRD with male infertility and MMAF using Cep78−/− mice." (PMID 36756949, 2023). "Cep78 deletion also caused male infertility and MMAF, with disordered ‘9+2’ structure and triplet microtubules in sperm flagella." (PMID 36756949, 2023). "In conclusion, we identify CEP78 as a causative gene for a type of syndrome involving CRD and male infertility." (PMID 36756949, 2023). "Deletion of Cep78 triggered male infertility, spermatogenesis defects, aberrant sperm flagella structures and manchette formation, and abnormal spermatid centriole length in male mice." (PMID 36756949, 2023). "While this study was under review, another lab in parallel reported similar findings that loss of Cep78 caused CRD, MMAF, and male infertility." (PMID 36756949, 2023). "Here, we report CEP78 as a causative gene of a particular syndrome including CRD and male infertility with multiple morphological abnormalities of sperm flagella (MMAF) both in human and mouse." (PMID 36756949, 2023). "Defect of Ift20 or Ttc21 could cause male infertility and MMAF, which also observed in Cep78 knockout mice and the patient with Cep78 mutation." (PMID 36756949, 2023). "Taken together, Cep78 deletion decreases count, motility and progressive motility of sperm, morphological abnormalities of sperm head, and flagella in mice, as well as dysregulated sperm proteins, thus accounting for male infertility." (PMID 36756949, 2023). "Cep78−/− mice present male infertility and morphological abnormalities of sperm." (PMID 36756949, 2023). "To further explore the underlying causes of male infertility of Cep78−/− mice, we assessed the concentration, motility, and progressive motility of sperm isolated from cauda epididymis using computer-assisted sperm analysis (CASA), and all three parameters were decreased upon Cep78 deletion." (PMID 36756949, 2023). "Despite these findings, the biological function of Cep78, especially its function and mechanism in CRD with male infertility, has not been well understood yet." (PMID 36756949, 2023).
ciliopathies (2 papers, 2021 to 2022). "Five of our probands exhibited ciliopathies due to variants in ALMS1 (Alström syndrome) and CEP78 (CRDHL1)." (PMID 34148116, 2022). "In summary, available data derived from human patients indicates that depletion of CEP78 leads to elongation of primary cilia at the cellular level, which manifests in ciliopathy phenotypes at the organism level." (PMID 34259627, 2021). "Several studies have shown that loss-of-function mutations in CEP78 are causative of ciliopathy characterized by CRDHL, and that cells lacking CEP78 display reduced ciliation frequency or abnormally long cilia." (PMID 34259627, 2021).
Infertility (2 papers, 2022 to 2024). "Some of these genes were also associated with male fertility or infertility in mammals (e.g., CEP78, GPER1)." (PMID 38540441, 2024). "Some of the genes presented, such as CCSER1, GNAQ, NCOA2, SNRK, and TSPO, have been previously associated with fertility traits in livestock species or related to infertility in human patients (CEP78 and GPER1)." (PMID 38540441, 2024).
goiter (1 paper, 2024). Enlargement of the thyroid gland usually caused by lack of iodine in the diet, hyperthyroidism, or thyroid nodules. "The results showed that the relative levels of CEP78 mRNA were significantly lower in thyroid cancer tissues than in goiter tissues (p = 0.002)." (PMID 39518001, 2024). "CEP78 may serve as a promising molecular biomarker for differentiating between thyroid carcinoma and goiter tissues, and, furthermore, it could act as a predictor of metastasis to lateral cervical lymph nodes." (PMID 39518001, 2024). "Using a quantitative real-time polymerase chain reaction, the expression of mRNA CEP78 and WDR62 was assessed in 40 samples of thyroid carcinoma tissue and 40 samples of goiter tissue." (PMID 39518001, 2024).
oligoasthenoteratozoospermia (1 paper, 2023). A form of male infertility that is characterized by a combination of low number or oligozoospermia, poor motility or asthenozoospermia, and abnormal shape or teratozoospermia of sperms. "The patient in our study showed phenotype of oligoasthenoteratozoospermia with MMAF, consistent with the phenotype observed in Cep78 knockout mice." (PMID 36756949, 2023).
Phosphoserine aminotransferase deficiency (1 paper, 2021). Phosphoserine aminotransferase deficiency is an extremely rare form of serine deficiency syndrome (see this term) characterized clinically in the two reported cases to date by acquired microcephaly, psychomotor retardation, intractable seizures and hypertonia. "This deletion encompasses the CEP78 and PSAT1 (MIM #610936) genes, the latter of which has so far only been implicated in recessive phosphoserine aminotransferase deficiency (MIM # 610992) and Neu-Laxova syndrome 2 (MIM # 616038)." (PMID 33968938, 2021).
cancer (1 paper, 2016). A tumor composed of atypical neoplastic, often pleomorphic cells that invade other tissues. "Centrosomal protein 78 (CEP78) has been characterized as a component of the centrosome required for the regulation of centrosome-related events during the cell cycle, but its role in human cancers remains unclear." (PMID 27357513, 2016).
tumor (1 paper, 2016). "The silencing of CEP78 was closely associated with large tumor size, advanced tumor stage, lymphatic metastasis, and distant metastasis." (PMID 27357513, 2016). "Low CEP78 expression was significantly associated with poor differentiation (P = 0.003), large tumor size (P = 0.017), lymphatic metastasis (P = 0.034), distant metastasis (P = 0.029), and advanced stage (P = 0.011)." (PMID 27357513, 2016). "CEP78 mRNA levels were significantly lower in most tumor tissues (5 out of 8) than in normal tissues." (PMID 27357513, 2016). "CRC patients with low CEP78 expression had a higher tendency to exhibit poor differentiation (P = 0.003), large tumor size (P = 0.017), lymphatic metastasis (P = 0.036), distant metastasis (P = 0.019), and advanced stage (P = 0.008)." (PMID 27357513, 2016). "The anti-tumor effect of CEP78 was further supported because CEP78 overexpression halted the growth of CRC xenografts." (PMID 27357513, 2016). "Surprisingly, we found that high CEP78 expression was detected in 30.0% (71/237) of samples of tumor tissues and 89.2% (141/158) of samples of adjacent normal tissues (P < 0.001)." (PMID 27357513, 2016). "The expression level of CEP78 was significantly lower in tumor tissues than in the adjacent normal tissues (P < 0.01)." (PMID 27357513, 2016). "In sharp contrast, tumor growth was much slower in groups with CEP78 overexpression compared with the control groups, as indicated by the decreased weight and volume of tumors." (PMID 27357513, 2016). "Because patients with CRC often experience metastasis to the lymph nodes, liver, and lungs at late stages, CEP78 may serve as a predictor for tumor metastasis in CRC." (PMID 27357513, 2016). "CEP78 might function as a tumor suppressor and serve as a novel prognostic marker in CRC." (PMID 27357513, 2016). "Overexpression of CEP78 in CRC cells significantly reduced cell viability and colony formation in vitro and halted tumor growth in vivo." (PMID 27357513, 2016). "Moreover, multivariate analysis showed that tumor size, distant metastasis, and tumor stage (P < 0.05), but not CEP78 expression (P = 0.191), were independent prognostic indicators in patients with CRC." (PMID 27357513, 2016). "Overall, CEP78 was found to be mainly distributed in the cytoplasm of tumor and non-tumor cells." (PMID 27357513, 2016).
CEP78 also shares sentences with these, for which no sentence is quoted: retinal degeneration (2 papers); Alström syndrome (1); autosomal recessive cone rod dystrophy (1); Blindness (1); colon cancer (1); colorectal cancer (1); cone dystrophy (1); cystic kidney disease (1); deaf (1); genetic disorders (1); Hearing impairment (1); retinal disease (1); retinitis pigmentosa (1); retinopathy (1); sensorineural hearing loss (1); thyroid carcinoma (1).